EGFR (epidermal growth factor receptor)
Diseases named in the same sentence as EGFR in open-access papers (continued):
Sharing a sentence is not in itself a finding about the gene and the disease.
tumor (continued). "To test the anti-tumour activity of IgA EGFR in an immunocompetent tumour model we used the well-established lung metastasis model with B16F10 cells." (PMID 23918228, 2013). "Here, we report the finding that treatment with EGFR inhibitors of various tumor cells, when stimulated with hepatocyte growth factor (HGF) and EGF, results in transient upregulation of phosphorylated AKT." (PMID 23812422, 2013). "IgA1 and IgA2 EGFR have similar target affinity and are as potent as cetuximab in eliciting Fab-mediated anti-tumour effects, such as inhibition of tumour growth and internalization of EGFR." (PMID 23918228, 2013). "In the case of EGFR, improved tumor uptake and intratumor distribution were achieved by using VHHs (15-kDa antibody fragments consisting of only the Vh domain of the heavy-chain-only antibodies from camelids)." (PMID 23184608, 2013). "Collectively, these data obtained using two xenograft models show effective anti-tumour activity by IgA2 EGFR in vivo against a tumour cell line with endogenous EGFR expression at two different anatomical locations." (PMID 23918228, 2013). "In previous animal studies we found that EGFR and Kras mRNA were significantly decreased in tumor tissue from mice treated with unspecific COX inhibition." (PMID 24171795, 2013). "Epidermal growth factor receptor (EGFR) is frequently aberrantly expressed in cancer, and abnormal signalling downstream of this receptor contributes to tumour growth." (PMID 24376686, 2013). "Along the same lines, patients with high tumor nuclear ERα(nucl) and high EGFR have significantly reduced progressive free survival (hazard ratio: 4.09) compared to patients with low ERαnucl and low EGFR levels, as estimated with Kaplan-Meier analyses." (PMID 24970177, 2013). "The secreted fusion protein was functionally active, and displayed specific binding to EGFR-overexpressing tumor cells as well as selective target cell killing in the presence of an endosomolytic activity." (PMID 23573299, 2013). "Taken together, we confirmed that IgA EGFR is more efficient than cetuximab in tumour cell killing by human myeloid effector cells." (PMID 23918228, 2013). "Similar to P22, P6 tumor cells in NBM still retained EGFR amplification, but the expression of EGFR was markedly reduced." (PMID 24349039, 2013). "Daoy cells were employed as the model system to identify tumor-relevant cooperation response genes (CRGs), which were synergistically regulated by combined HH and EGFR signaling." (PMID 23762360, 2013). "To date, the majority of published data assessing such molecular techniques are derived from primary tumour analyses; however, studies assessing the suitability of EGFR testing in metastatic tissues are considerably less extensive." (PMID 23892415, 2013). "EGFR participates in several essential tumorigenic mechanisms, such as tumor survival, invasion, angiogenesis, and metastatic spread." (PMID 23555641, 2013). "AREG mRNA reflects EGFR signalling in KRAS wild type tumours, predicting for cetuximab efficacy when high and failure when low." (PMID 23374602, 2013). "In vivo studies with athymic nude mice revealed a 56% reduction in tumor volume after 45 days resulting from a robust decrease in EGFR expression and pAkt expression as shown by western blot." (PMID 24244833, 2013). "Preclinical studies showed that the anti-EGFR monoclonal antibody C225 (cetuximab) enhanced the radiosensitivity of tumor cells." (PMID 23509762, 2013). "It was also seen that P276-00 treatment reduced expression of tumor micro-environment proteins such as IL-6, secreted EGFR and HSPA8." (PMID 23414419, 2013).
tumor (continued). "The results of this study indeed show for the first time that internal irradiation of CAL33 tumor cells with alpha-emitter 213Bi-anti-EGFR immunoconjugates is equally efficient in eradication of hypoxic and normoxic cells." (PMID 23724085, 2013). "We demonstrate potent anti-tumour activity of IgA2 EGFR in vivo using A431 tumour cells in both a lung and peritoneal xenograft model in severe combined immune deficiency (SCID) mice." (PMID 23918228, 2013). "Targeting of TAAs with monoclonal antibodies can also provide avenues to achieve tumor inhibition as has already been demonstrated in practice with cetuximab (Erbitux; against EGFR), rituximab (Rituxan; targeting CD20), and tositumomab (targeting CD20)." (PMID 23308131, 2013). "Subsequently, we confirmed well-characterized oncogenes among tumor-related loci (such as EGFR and KIT) and detected novel genes that gained chromosome sequences (such as AASS, HYAL4, NDUFA5 and SPAM1) in both LGG and HGG." (PMID 23451178, 2013). "Several signaling pathways have been reported to promote tumor development in intestinal tumorigenesis, including Wnt and epidermal growth factor receptor (EGFR)." (PMID 24279644, 2013). "In multivariate survival analysis, EGFR (p = 0.023), patients' age (p<0.001), Dukes' stage (p<0.001), tumour location (p = 0.001), and WHO grade (p = 0.033) were independent prognostic factors." (PMID 24204699, 2013). "In particular, the epidermal growth factor receptor (EGFR) appears to play an important role in tumor growth, survival, and therapeutic resistance." (PMID 23383403, 2013). "This antibody is advantageous because the mutant receptor is not expressed in normal tissue, so should minimize side effects resulting from antibody binding to EGFR expressed on non-tumor cells." (PMID 24349829, 2013). "As the first small inhibitor for EGFR, gefitinib induce dramatic clinical responses and improve progression-free survival, through inhibition of EGFR-driven signals for tumor cells survival and proliferation." (PMID 23937717, 2013). "Upregulation of SHP2y584-GRB2 interaction in tumor cells suggest that Erk activation is driven through RTKs (EGFR, VEGFR) other than PDGF and FGF to promote cell proliferation and survival." (PMID 23826330, 2013). "The injection of fluorescent tracers targeted to molecular receptors over-expressed in tumors, such as EGFR, provide a promising means of improving tumor contrast during surgical resection." (PMID 23593208, 2013). "From these experiments we concluded that IgA2 EGFR elicits in vivo anti-tumour activity that was strictly dependent on the presence of FcαRI, indicating that in this model system Fc-independent effector mechanisms did not contribute to the observed effects." (PMID 23918228, 2013). "High EGFR amplification was detected in the tumor cells from the invasive xenografts while corresponding patient tumors showed variable levels of EGFR amplification in the tissue sections." (PMID 23429996, 2013). "Immunohistochemical (IHC) studies of CRC tumours indicated that patients with EGFR-positive tumours benefit from anti-EGFR therapy." (PMID 23356214, 2013). "The EGFR has been known to play a key role in the activation of DNA repair and anti-apoptotic proteins, as well as tumor cell repopulation after irradiation." (PMID 24252457, 2013). "In preclinical models, 17-AAG sensitizes the anticancer activity of paclitaxel by rapidly degrading key signaling proteins such as HER2, EGFR and Akt in tumor cells." (PMID 23505544, 2013). "Several studies have shown that 18F-FLT PET is useful for the early evaluation of tumor response to anti-EGFR targeted therapy such as erlotinib and cetuximab." (PMID 24191959, 2013). "This study observed that in KRAS wild-type patients, the objective response to anti-EGFR therapy was 0% in BRAF mutant tumours versus 36.3% in BRAF wild-type tumours." (PMID 23356214, 2013).
tumor (continued). "Nine tumours were amplified (>2 alleles) for the HER2 gene (range 3-14 alleles) and one tumour was amplified for the EGFR/HER1 gene." (PMID 23991224, 2013). "Consistently, at 48h after LPEI/siRNA-EGFR complexes injection, tumor western blot analysis showed significant decrease (51%) in EGFR protein expression as compared with the non-specific control group." (PMID 27234384, 2013). "In all four tumor cell lines, EGFR dimerization and specific binding of hEGF increased with increased gefitinib dose." (PMID 23748900, 2013). "The detailed analysis of EGFR homeostasis pathway in HNSCC is warranted to develop proper therapeutic measure of the tumor." (PMID 23675485, 2013). "Another approach for targeting EGFR is vaccines that elicit an immune response against EGFR-expressing tumor cells." (PMID 24349829, 2013). "Despite this difference, cetuximab and IgA2 EGFR were both effective in suppressing tumour outgrowth in FcαRI Tg mice." (PMID 23918228, 2013). "HNSCC tumors get nourished due to its microenvironment and are well supplied with soluble epidermal growth factor receptor (EGFR) and cytokine (IL-6), which play a critical role in tumor aggressiveness and their response to various therapies." (PMID 23414419, 2013). "Inhibition of EGFR has been shown to induce tumor vascular changes known as “vascular normalization” through an indirect decrease of VEGF production, and this was shown to improve chemotherapy or radiotherapy efficacy." (PMID 23874590, 2013). "Here, we emphasize the role of the miRs most commonly involved in facilitating or suppressing aberrant EGFR signaling in a variety of tumor types." (PMID 24349829, 2013). "Taken together, EGFR represents an attractive target for small molecules or antibodies in applications such as tumor-targeted imaging and therapy." (PMID 23710458, 2013). "More recently, efficient tumour cell killing by IgA EGFR by differentiated human macrophages was demonstrated even at low E:T ratios." (PMID 23918228, 2013). "These early changes in tumor proliferation activity were confirmed by our pathological studies that including immunohistochemical staining of the Ki-67 and phospho-EGFR assay." (PMID 24191959, 2013). "Although the inhibition of EGFR activation significantly reduced tumor growth and invasion in our model, tumor cells had the capacity to induce an angiogenic program and thereby escape the invasion block as shown by stable expression of dominant-negative EGFR." (PMID 23429996, 2013). "Notch pathway seems to be intimately coupled to MAP-kinase signalling with proven crosstalk between the Notch pathway and EGFR signalling, which has been revealed in tumour angiogenesis." (PMID 23998913, 2013). "It was previously shown that IgG1 EGFR antibodies have a dual mode of action: at high antibody concentration the anti-tumour effect is primarily achieved by growth inhibition, whereas at lower antibody concentration they act via ADCC." (PMID 23918228, 2013). "Multiple anti-EGFR agents have been developed and have exhibited significant anti-tumor activities in these cancers." (PMID 23637996, 2013). "Microglia derived from brain cortices of newborn mice were shown to lyse human tumor cell lines expressing different levels of epidermal growth factor receptor (EGFR) in the presence of a monoclonal antibody specific to EGFR." (PMID 23983766, 2013). "Constitutively active KRAS mutations have been found to be involved in various processes of cancer development, and render tumor cells resistant to EGFR-targeted therapies." (PMID 23355875, 2013). "In vivo studies in over-expressing, EGFR-tumor bearing mice showed a reduction in the average tumor size of more than 90% as a result of this combined therapy." (PMID 24105401, 2013). "Secreted GrB-T fusion protein displayed specific binding to EGFR-overexpressing tumor cells, enzymatic activity, and selective target cell killing in the presence of an endosomolytic activity." (PMID 23573299, 2013).
tumor (continued). "In conclusion, we demonstrated that despite tumor progression after treatment with EGFR-TKIs, NSCLCs with MET amplification are still dependent on EGFR signaling." (PMID 24167634, 2013). "Our data showed that tumor cell viability was significantly reduced and tumor cell apoptosis enhanced by irradiation following inhibition of both EGFR and IGF1R, as compared to irradiation treatment alone or irradiation plus blocking of either receptor." (PMID 23950876, 2013). "Further, this study also identifies the potential of the extracted polyphenols on major tumor progression molecular targets including NFκB, EGFR, kRAS, STAT3, VEGF, AKT, TERT, FGFA, BCl2 and PDGFA." (PMID 23613993, 2013). "In conclusion, we have defined a NGS protocol based on the 454 GS-Junior platform for the analysis of EGFR and validated it with unselected limited tumor samples routinely submitted for molecular diagnosis to three different Italian laboratories." (PMID 24376723, 2013). "Small, fluorescently labeled proteins with high affinity to tumor receptors show considerable potential for aiding in surgical visualization and the targeted Affibody examined shows excellent potential for EGFR positive tumor targeting." (PMID 23593208, 2013). "A negative correlation was seen between the 74 kDa COX-2 protein and the extra- and intracellular parts of EGFR in tumor tissue." (PMID 24171795, 2013). "In ET samples, as expected, the majority of tumor cells exhibited strong specific EGFR immunopositivity." (PMID 23472076, 2013). "Since gefitinib has been shown to induce STAT3 activation and subsequent Akt recovery, we went to assess the anti-tumor efficacy of combinational inhibition of EGFR and STAT3." (PMID 24280348, 2013). "The antineoplastic activity of the CIK cells directed using the EGFR/CD3 BsAb in vivo was analyzed by tumor growth and tumor reduction assays." (PMID 23833649, 2013). "EGFR mutations, gene copy number gains, and MASI occurring together in tumor cells appear to synergize to effect a more malignant phenotype than these alterations individually." (PMID 23418425, 2013). "EGF promotes tumor development amplifying the expression its tyrosine kinase epidermal growth factor receptor (EGFR) by increasing ligand-activated signaling through of its own receptor." (PMID 24294521, 2013). "FISH analysis and immunohistochemistry for EGFR showed high EGFR amplification and strong expression in the tumor cells, respectively, indicating that the xenograft model selected for highly EGFR amplified/expressing cells." (PMID 24349039, 2013). "While upregulation of the AR-target gene p21WAF1 promoted tumor cell proliferation through the MAPK pathway, hyperactivation of MAPK by concurrent AR and EGFR-signaling pathways caused tumor growth suppression." (PMID 24324894, 2013). "Several known mechanisms to explain the tumor suppressive role by miRNAs modifications are epigenetic aberration by targeting the DNA methyltransferases, regulation of the epidermal growth factor receptor expression, and regulation of tumor angiogenesis." (PMID 23967217, 2013). "On the other hand, in in vivo, [125I]PYK tumor accumulation was found decreases by the EGFR-TK inhibitors pretreatment and a slight decrease by VEGFR inhibitor I pretreatment." (PMID 23494210, 2013). "Paradoxically, several studies have shown that miR-7 also acts as tumor suppressor by directly targeting EGFR itself." (PMID 24349829, 2013). "In in vitro experiments, binding of nimotuzumab and subsequent inhibition of the EGFR phosphorylation was detected only for tumor cell lines with medium or high levels of EGFR expression (104 receptors per cell or higher)." (PMID 23637683, 2013).
tumor (continued). "The frequency of EGFR mutations in NSCLC is known to be associated with many factors, including race, gender, smoking status, and tumor histology." (PMID 24351833, 2013). "For example, in EGFR-wild type NSCLCs, 0-10% of patients (median, 8%) experience a >30% reduction in tumor diameter with erlotinib or gefitinib, and 12-38% (median, 22%) experience a >10% reduction in tumor diameter." (PMID 23587187, 2013). "The increased activity of EGFR promotes tumor growth through many different mechanisms, promoting survival, invasion, and angiogenesis." (PMID 23977117, 2013). "The EGFR-activated tumor subpopulation is an important target for therapy as these cells are highly invasive and, accordingly, have the capacity to escape current therapies." (PMID 23429996, 2013). "The liposomes trapped in the tumor interstitium by this EPR-effect have substantially increased cellular binding when liposomes were conjugated with anti-EGFR antibody." (PMID 24175095, 2013). "We observed under serum monolayer conditions, that nestin positive or nestin and SMA double positive rat stromal cells outgrew EGFR amplified tumor cells, while serum spheroid cultures preserved tumor cells with EGFR amplification." (PMID 24349039, 2013). "The need to identify tumours addicted to EGFR signalling and thus amenable to anti-EGFR therapeutic modulation became apparent early on, as response rates to cetuximab regimens in unselected patient populations were typically lower than 30%." (PMID 23374602, 2013). "Taken together, these results demonstrate that the original patient tumor and xenograft express EGFR and, of those examined, EGFR is the most activated kinase in the xenograft." (PMID 24260133, 2013). "Only a few markers of EGFR addiction can be already defined, each one of them for a specific tumor type and a particular disease stage." (PMID 23637683, 2013). "Mouse monoclonal antibodies raised against the EGFR (mAb 225IgG1 and mAb 528 IgG2a) block the binding of EGFR ligands and inhibit proliferation in vitro, tumor growth in vivo, and EGF-activated tyrosine kinase activity." (PMID 24276379, 2013). "EGFR+/TATI+ correlated with histology occurring more often in adenocarcinomas than in other histological tumour types (p = 0.005), and varied by WHO grade, being most often present in highly and moderately differentiated tumours (p<0.001)." (PMID 24204699, 2013). "Given the sensitivity of EGFR-mutated SCLC to cytotoxic chemotherapies, re-biopsy for detecting tumor transformation can prove highly beneficial for patients." (PMID 24195468, 2013). "Specifically, although erlotinib is considered a specific EGFR inhibitor, it has been reported to inhibit other kinases including ErbB2 and Src family members in other tumor types." (PMID 24260133, 2013). "COX and EGFR are thus suggestive targets for combinatorial treatment of CRC since both pathways involve tumor progression and are reported to show increased activities in CRC tissue." (PMID 24171795, 2013). "Using FcαRI transgenic mice, we demonstrated significant in vivo anti-tumour activity of IgA2 EGFR against A431 cells in peritoneal and lung xenograft models, as well as against B16F10-EGFR cells in a lung metastasis model in immunocompetent mice." (PMID 23918228, 2013). "EGFR-targeted CAR T cells have demonstrated anti-tumor efficacy both in vitro and in vivo with low systemic toxicity." (PMID 24349829, 2013). "The aim of this study is to examine the effect of chemotherapy combined with cetuximab (C225, an anti-EGFR mAb) on the immune state of tumor environment, and the correlation of that effect and the clinical efficacy." (PMID 24028754, 2013). "It has been reported that EGFR is closely correlated with tumor proliferation, metastasis, apoptosis, angiogenesis, sensitivity to radiotherapy and/ or chemotherapy and drug resistance." (PMID 23946790, 2013).